FOXF1 (forkhead box F1)
Description:
Probable transcription activator for a number of lung-specific genes.
Synonyms: FKHL5; FREAC1; ACDMPV
Tractability: PROTAC: ubiquitination databases record sites on it.
Gene: Protein-coding gene on chromosome 16 (86,510,527 to 86,515,422, forward strand). Ensembl gene ENSG00000103241.
Subcellular location: Nucleus
Subcellular location (Human Protein Atlas): Nucleoplasm
Pathways (Reactome):
Cell-Cell communication: Regulation of CDH11 gene transcription
Developmental Biology: Formation of lateral plate mesoderm
Gene Ontology:
Molecular function: DNA binding; DNA-binding transcription activator activity, RNA polymerase II-specific; RNA polymerase II transcription regulatory region sequence-specific DNA binding; DNA-binding transcription factor activity, RNA polymerase II-specific; RNA polymerase II cis-regulatory region sequence-specific DNA binding; sequence-specific DNA binding; DNA-binding transcription factor activity; transcription cis-regulatory region binding
Biological process: blood vessel development; cardiac left ventricle morphogenesis; digestive tract development; ductus arteriosus closure; embryonic digestive tract morphogenesis; embryonic ectodermal digestive tract morphogenesis; endocardial cushion development; heart development; in utero embryonic development; lung development; lung vasculature development; midgut development; morphogenesis of a branching structure; pancreas development; positive regulation of DNA-templated transcription; positive regulation of transcription by RNA polymerase II; respiratory tube development; trachea development; ureter development; venous blood vessel development; animal organ morphogenesis; regulation of transcription by RNA polymerase II; regulation of DNA-templated transcription; system development
Cellular component: chromatin; nucleus; transcription regulator complex
Genetic constraint (gnomAD): Loss-of-function variants: 9 observed, 22.93 expected, observed/expected ratio (o/e) 0.39, 90% interval 0.24 to 0.69. The synonymous counts are far from expectation, so gnomAD's model fits this gene poorly and the ratio says little. Missense variants: 499 observed, 518.02 expected, observed/expected ratio (o/e) 0.96, 90% interval 0.89 to 1.04. Synonymous variants: 330 observed, 245.75 expected, observed/expected ratio (o/e) 1.34, 90% interval 1.23 to 1.47.
Homologues: Orthologues: chimpanzee FOXF1 (99% identical), macaque FOXF1 (99% identical), pig FOXF1 (96% identical), dog FOXF1 (96% identical), rabbit FOXF1 (95% identical), guinea pig FOXF1 (95% identical), mouse Foxf1 (93% identical), rat Foxf1 (93% identical), tropical clawed frog foxf1 (77% identical), zebrafish foxf1 (76% identical). Paralogues in human: FOXC2 (27% identical), FOXC1 (26% identical), FOXB1 (23% identical), FOXD3 (23% identical), FOXD4 (23% identical), FOXD1 (23% identical), FOXE1 (23% identical), FOXE3 (23% identical), FOXA2 (22% identical), FOXD2 (22% identical), FOXL2 (22% identical), FOXD4L3 (22% identical), and 29 more.
Diseases named in the same sentence as FOXF1 in open-access papers:
FOXF1 is named in the same sentence as 135 diseases in open-access papers, as found by Europe PMC text mining. Sharing a sentence is not in itself a finding about the gene and the disease. The quoted sentences say what the papers report.
alveolar capillary dysplasia (31 papers, 2009 to 2025). "Alveolar capillary dysplasia with misalignment of pulmonary veins (ACD/MPV) is a fatal congenital lung disorder strongly associated with genomic alterations in the Forkhead box F1 (FOXF1) gene and its regulatory region." (PMID 39497128, 2024). "LoF variants in FOXF1 are a known cause of alveolar capillary dysplasia with misalignment of pulmonary veins." (PMID 38685090, 2024). "Mutations in the FOXF1 gene, a key transcriptional regulator of pulmonary vascular development, cause Alveolar Capillary Dysplasia with Misalignment of Pulmonary Veins, a lethal lung disease affecting newborns and infants." (PMID 38898031, 2024). "Deletions or point mutations in FOXF1 gene locus are linked to Alveolar Capillary Dysplasia with Misalignment of Pulmonary Veins (ACDMPV), a lethal congenital disorder of newborns and infants." (PMID 38589650, 2024). "Heterozygous mutations of FOXF1 are causal in alveolar capillary dysplasia, a fatal disease of infancy with misaligned pulmonary arteries and veins and extensive occlusive changes in pulmonary arteries similar to those observed in PAH31." (PMID 37989727, 2023). "Heterozygous SNVs or CNV deletions involving the FOXF1 gene, or its distant enhancer, are causative for 80–90% of cases of alveolar capillary dysplasia with misalignment of pulmonary veins." (PMID 37865798, 2023). "Point mutations in FOXF1 such as S52F, result in a severe pediatric lung disease called Alveolar capillary dysplasia with misalignment of pulmonary veins (ACDMPV) which is fatal without neonatal lung transplantation." (PMID 37363726, 2023). "Heterozygous loss of function of the FOXF1 gene has been found in 80–90% of neonates with histologically verified alveolar capillary dysplasia with misalignment of pulmonary veins (ACDMPV), a lethal lung developmental disorder." (PMID 37865798, 2023). "FOXF1 heterozygous point mutations and genomic deletions have been reported in newborns with the neonatally lethal lung developmental disorder, alveolar capillary dysplasia with misalignment of pulmonary veins (ACDMPV)." (PMID 27638768, 2016). "FOXF1 loss of function mutation have been so far identified in alveolar capillary dysplasia with misalignment of pulmonary veins (ACD/MPV), a lung disease different from PCH." (PMID 26462560, 2015). "Notably, endothelial FOXF1 inhibits lung fibrosis in mice, and mutations cause congenital alveolar capillary dysplasia with misalignment of pulmonary veins in humans." (PMID 39566559, 2024). "Deletion and inactivating point mutations in FOXF1 gene locus are associated with Alveolar Capillary Dysplasia with Misalignment of Pulmonary Veins (ACDMPV), a congenital pulmonary disorder characterized by the loss of pulmonary capillaries and respiratory insufficiency in neonates and infants." (PMID 38589650, 2024). "The deletion of heterozygous copy number variants and point mutations in FOXF1 is the primary cause of alveolar capillary dysplasia with misalignment of pulmonary veins, which is a rare and fatal disease characterized by severe progressive hypoxia and pulmonary hypertension." (PMID 36277750, 2022). "FOXF1 is crucial to the development of the lung, and its haploinsufficiency may cause lung deformity, such as severe alveolar capillary dysplasia with misalignment of pulmonary veins." (PMID 32370197, 2020). "Furthermore, FOXF1 also plays a vital role in the development of pulmonary alveoli and vasculature, whereas any deletions or mutations in the FOXF1 gene are believed to cause alveolar capillary dysplasia with misalignment of pulmonary veins." (PMID 32370197, 2020). "Heterozygous deletions and point mutations in the FOXF1 gene locus were found in patients with Alveolar Capillary Dysplasia with Misalignment of Pulmonary Veins (ACD/MPV), a rare congenital disorder characterized by severe defects in development of the alveolar capillary network." (PMID 26625197, 2016).
alveolar capillary dysplasia (continued). "Interestingly, patients with microdeletion/mutation of the FOXF1 gene display multiple phenotypes, such as alveolar capillary dysplasia with misalignment of pulmonary veins (ACD/ MPV), esophageal atresia with/without tracheoesophageal fistula (EA/TEF), and the VATER/VACTERL association." (PMID 34671097, 2021). "Here, the authors discovered four genomic regions that control cell type-specific activity of Foxf1 during lung development and show that disrupting these regions via genetic deletions leads to alveolar capillary dysplasia." (PMID 38898031, 2024). "Interestingly, heterozygous inactivation of FOXF1 has been associated with the “Alveolar Capillary Dysplasia with Misalignment of Pulmonary Veins” syndrome (ACDMPV: OMIM 265380) in human newborns." (PMID 28797033, 2017). "Foxf1+/− mice exhibit alveolar capillary dysplasia (ACD), which results from abnormal development of pulmonary capillaries." (PMID 26625197, 2016). "Unlike alveolar capillary dysplasia, which has been linked to variants in FOXF1, the genetic basis of acinar dysplasia remains poorly explained." (PMID 41417852, 2025). "FOXF1 has been confirmed to affect pulmonary angiogenesis in alveolar capillary dysplasia." (PMID 39010027, 2024). "Heterozygous loss-of-function of the mesenchymal forkhead transcription factor gene FOXF1 at chr16q24.1 has been found in 80–90% of neonates with a lethal lung developmental disorder, alveolar capillary dysplasia with misalignment of pulmonary veins (ACDMPV, MIM 265380)." (PMID 37888207, 2023). "This enhancer was originally described as ~60 kb-large regulatory region based on the overlap of heterozygous copy number variant (CNV) deletions detected in patients with Alveolar Capillary Dysplasia with Misalignment of Pulmonary Veins (ACDMPV, MIM: 265380) due to FOXF1 haploinsufficiency." (PMID 33513839, 2021). "In the group of fetuses with the isolated increased nuchal translucency a small interstitial 16q24.1 deletion was identified, involving FOXF1 gene (Alveolar capillary dysplasia with misalignment of pulmonary veins, ACDMPV, OMIM#265380) and FOXC2 gene (Lymphedema-distichiasis syndrome, OMIM#153400)." (PMID 27846804, 2016). "Alveolar capillary dysplasia with or without misalignment of the pulmonary veins (ACD/MPV) is a lethal congenital lung disorder associated with heterozygous genomic alterations in the Forkhead Box F1 (FOXF1) gene locus." (PMID 34325731, 2021). "Several cases of genetic deletions encompassing the neighboring protein coding gene FOXF1, and also FENDRR have been observed in neonates with the lethal lung disorder ‘alveolar capillary dysplasia with misalignment of pulmonary veins’ (ACD/MPV)." (PMID 24381249, 2013).
breast carcinoma (22 papers, 2013 to 2026). "Early studies indicated that FOXF1 promoted the development of cancers, including prostate cancer, osteosarcoma, and breast cancer." (PMID 35468741, 2022). "In the breast cancer tissues, the most robust correlations have been detected between lnc_ZFP161/ lnc_FOXF1, CAMK2D/ lnc_ZFP161 and CAMK2D / lnc_FOXF1 (r = 0.86, 0.71 and 0.64 respectively)." (PMID 33742056, 2021). "We included ERα and FOXA1 (in lieu of FOXF1) based on their known relevance and protein-protein interactions in breast cancer, and PITX1 for relevance in other cancers and its novelty in ovarian cancer." (PMID 34215221, 2021). "In a few previous studies, FOXF1 was demonstrated as a tumor suppressor, and it was found downregulated in certain types of cancers, including prostate and breast cancer tissues, when compared to normal." (PMID 32370197, 2020). "On the contrary, the functional role of FOXF1 remains controversial, as various studies also demonstrated that FOXF1 expression was inhibited in various tumor types including lung, prostate, bladder, ovarian, and breast cancers." (PMID 32370197, 2020). "The lncRNA, FENDRR, which is produced from a spliced long non-coding RNA transcribed bidirectionally with FOXF1 on the opposite strand, is down-regulated in both breast cancer and gastric cancer." (PMID 31106044, 2019). "An interesting observation is that four of the six methods have chosen FOXF1 as the first gene to split, indicating that FOXF1 is closely related to breast cancer and the effectiveness of radiotherapy." (PMID 30598067, 2018). "FOXF1, a potential tumor suppressor gene that is epigenetically silenced in breast cancer, plays a critical role in embryonic development as well as in cell cycle processes that maintain genomic stability." (PMID 28404937, 2017). "Clarifying the role of FoxF1 in carcinogenesis would be of great importance in order to evaluate the potential of FoxF1 as a molecular target against breast cancer invasion and metastasis." (PMID 26908052, 2016). "Previous studies have shown FOXF1 to be epigenetically inactivated in breast cancer, suggesting its potential role as a tumor suppressor gene." (PMID 25472632, 2014). "Up-regulation of FOXF1 has been reported in breast cancer, rhabdomyosarcoma, and in colorectal adenocarcinomas." (PMID 25472632, 2014). "Most intriguing is the description of FOXF1 as an inducer of G1-S and S-G2 cell cycle arrest, indicating a possible role in oncogene-induced senescence in breast cancer." (PMID 23324568, 2013). "Conversely, other studies propose that FOXF1 may act as an oncogene in the metastatic progression of breast cancer." (PMID 40869921, 2025). "Furthermore, it acts as a breast cancer tumor suppressor, as it directly represses the expression of Ccnd1 and Foxf1, a potent inducer of epithelial-mesenchymal transition (EMT), invasiveness, and tumorigenicity." (PMID 37353485, 2023). "In HCC and breast cancer FOXF1 has been described as a tumor suppressor." (PMID 34257615, 2021). "Also, there is evidence that FOXF1 acts as a tumour suppressor, as it is inactivated by DNA methylation in breast cancer and its expression is reduced in prostate cancer." (PMID 30624614, 2019). "FoxF1 is highly expressed in invasive breast cancer cell lines compared to less invasive ones." (PMID 26908052, 2016). "With the purpose to narrow down the set of genes negatively regulated by NFI-C2 and positively regulated by FoxF1, we associated this microarray with a former microarray where we used the MDA-MB 436 breast cancer cell line, a mesenchymal-like cell line with high expression of FoxF1." (PMID 26908052, 2016). "In breast cancer tissues, the most robust correlations have been detected between lnc_ZFP161/lnc_FOXF1, CAMK2D/lnc_ZFP161 and CAMK2D/lnc_FOXF1." (PMID 33742056, 2021).
breast carcinoma (continued). "In breast cancer tissues, the most robust correlations have been detected between lnc_ZFP161/ lnc_FOXF1, CAMK2D/ lnc_ZFP161 and CAMK2D / lnc_FOXF1 (r = 0.86, 0.71 and 0.64 respectively)." (PMID 33742056, 2021). "All three are targets of inactivation in breast cancer and both FOXC1 and FOXF1 are subjected to promoter methylation." (PMID 23324568, 2013). "FOXF1 adjacent non-coding developmental regulatory RNA (FENDRR), also known as lncRNA FOXF1-AS1, is aberrantly expressed in various types of cancer, such as breast cancer, lung cancer, and chronic myelogenous leukemia." (PMID 33869020, 2021). "However, the levels of FoxF1 in breast carcinomas have not been rigorously investigated due to the lack of specific antibodies." (PMID 26908052, 2016). "FoxF1 is repressed by NFI-C2, which is lost during mammary tumor progression and almost universally absent in lymph node metastases." (PMID 26908052, 2016).
lung carcinoma (21 papers, 2014 to 2024). "Altogether, FOXF1 deficiency in endothelial cells stimulated lung tumorigenesis in orthotopic and chemically induced mouse models of lung cancer." (PMID 38589650, 2024). "This implies the anti-lung cancer activities of FOXF1; however, the detailed underlying mechanism needs to be investigated." (PMID 32370197, 2020). "FOXF1 has also been shown to contribute to the tumour-promoting properties of lung cancer-associated fibroblasts, including the production of hepatocyte growth factor and fibroblast growth factor-2, both of which promote tumour growth." (PMID 30624614, 2019). "Forkhead box F1(FoxF1) is associated with poor prognostic outcomes in some lung cancer subtypes." (PMID 35433472, 2022). "This implies that FOXF1 and its downstream molecules might act as molecular targets for the development of diagnostic and therapeutic tools against lung cancer." (PMID 32370197, 2020). "Endothelial-specific overexpression of FOXF1 normalized tumor vessels and inhibited the progression of lung cancer." (PMID 38589650, 2024). "Our results support the use of FOXF1-activating therapies for vascular normalization in lung cancers." (PMID 38589650, 2024). "Endothelial cell-specific deletion of Foxf1 stimulates lung cancer growth and metastasis, whereas FOXF1 overexpression in endothelial cells inhibits lung tumorigenesis." (PMID 38589650, 2024). "Altogether, FOXF1 increases tumor vessel stability, and inhibits lung cancer progression by stimulating FZD4/Wnt/β-catenin signaling in TECs." (PMID 38589650, 2024). "While endothelial-specific deletion of FOXF1 in mice destabilizes tumor vessels and promotes lung cancer growth and metastasis, the endothelial overexpression of FOXF1 normalizes tumor vessels and inhibits lung tumor progression." (PMID 38589650, 2024). "Epigenetic silencing of MPDZ inhibits growth and progression of lung cancer and epigenetic activation of FOXF1 confers cisplatin-resistant of NSCLC." (PMID 37060064, 2023). "In this study, we initially examined FOXF1 expression in lung cancer tissues and cell lines compared to those with normal tissues." (PMID 32370197, 2020). "In this context, our soft agar assay demonstrated a significantly inhibited anchorage-independent cell growth in highly expressing FOXF1 lung cancer cell lines, indicating the tumor-suppressing effect of FOXF1." (PMID 32370197, 2020). "To evaluate the effect of high expression of FOXF1 on lung cancer cell metastatic potential, we performed the wound healing assay, which shows the migration ability of cell lines." (PMID 32370197, 2020). "We selected six studies in this database which also revealed significantly lowered expression (4–19-fold) of FOXF1 gene in lung cancer compared to normal tissue." (PMID 32370197, 2020). "In this study, we examined the expression levels of FENDRR and FOXF1 in lung cancer patients through qRT-PCR." (PMID 32284793, 2020). "Taken together, FOXF1 significantly inhibited the cell growth and migration of lung cancer, largely via stimulating tumor suppressor p21 and inhibiting levels of cyclins, leading to an arrested cell cycle in the G1 phase." (PMID 32370197, 2020). "In our previous study, FOXF1 was identified as a reprogramming mediator that leads to stemness, when mesenchymal stem cells (MSCs) fuse with lung cancer cell, and its restoration leads to p21-regulated growth suppression in fusion progeny." (PMID 32370197, 2020). "In summary, this study identifies FENDRR and FOXF1 as novel potential tumour suppressor genes in lung cancer and that FENDRR acts by binding to unmethylated FOXF1 promoter." (PMID 32284793, 2020). "FENDRR and FOXF1 expression levels were quantified by qRT-PCR in 5 human lung cancer cell lines (A549, H441, H661, H838 and H460), displaying similar trend than in primary tumors." (PMID 32284793, 2020).